MIR6133 (microRNA 6133)
Synonyms: hsa-mir-6133
Gene: MicroRNA gene on chromosome 7 (133,290,881 to 133,290,988, forward strand). Ensembl gene ENSG00000276137.
Homologues: Orthologues: chimpanzee ptr-mir-6133 (100% identical).